OXTR (oxytocin receptor)
Diseases named in the same sentence as OXTR in open-access papers (continued):
Sharing a sentence is not in itself a finding about the gene and the disease.
adenomyosis (14 papers, 2014 to 2026). The growth of endometrial tissue inside the muscular wall of the uterine corpus. "Subsequently, a similar study was conducted using tissues with adenomyotic lesions derived from premenopausal women, indicating not only the overexpression of OXTR in adenomyosis-associated myometrium, compared to unaffected myometrium, but also significant morphological changes." (PMID 36835321, 2023). "The myometrium also contributes to the pathogenesis and pathophysiology of adenomyosis, as increased uterine contractility, which is induced by overexpression of the oxytocin receptor in women with symptomatic adenomyosis, and is associated with dysmenorrhoea, common in this disorder." (PMID 35773139, 2022). "Oxytocin receptor (OTR) expression in myometrium is elevated and correlates with uterine contractile amplitude and the severity of dysmenorrhea in women with adenomyosis." (PMID 41836349, 2026). "This retrospective cohort study with PSM aimed to explore the effects of oxytocin receptor antagonists on IVF outcomes among infertile women diagnosed with adenomyosis undergoing FET HRT cycles." (PMID 38997744, 2024). "Our investigation indeed uncovered a positive relationship between oxytocin receptor antagonist usage and decreased rates of early miscarriage among women with adenomyosis." (PMID 38997744, 2024). "Studies have shown variable expression of OXTR across the menstrual cycle and in response to endometrial pathologies, including endometriosis, adenomyosis and recurrent implantation failure." (PMID 37443771, 2023). "Oxytocin antagonists are being investigated for the use in adenomyosis treatment because overexpression of oxytocin receptor has been demonstrated in uteri with adenomyosis." (PMID 34362193, 2021). "Based on these findings, we hypothesized that administering an oxytocin receptor antagonist during ET could potentially improve IVF outcomes for women with adenomyosis." (PMID 38997744, 2024). "Multivariate analysis demonstrated a negative association between oxytocin receptor antagonist use and early miscarriage rates in women with adenomyosis (adjusted OR 0.32, 95% CI 0.11–0.95, P = 0.040)." (PMID 38997744, 2024). "In conclusion, the administration of an oxytocin receptor antagonist during FET may potentially decrease the early miscarriage rates in women with adenomyosis." (PMID 38997744, 2024). "Hence, our study aims to explore the effects of oxytocin receptor antagonist administration during frozen embryo transfer (FET) on IVF outcomes among infertile women with adenomyosis." (PMID 38997744, 2024). "Administering an oxytocin receptor antagonist during FET may reduce the early miscarriage rates in women with adenomyosis." (PMID 38997744, 2024). "Indeed, increased myometrial expression of the oxytocin receptor, along with increased uterine contractility, which correlated positively with the severity of dysmenorrhea, was found in women with adenomyosis." (PMID 37371555, 2023). "Overexpression of OXTR in adenomyosis-surrounding myometrium coupled with vasopressin receptor (VP1αR) expression in blood vessels and myometrium may contribute to altered microcirculation as well as increased uterine contractility." (PMID 35773139, 2022). "Abnormal expression of oxytocin receptor in the JZ of women with adenomyosis has been observed, which may explain the occurrence of hyperperistalsis and dysperistalsis, in turn leading to dysmenorrhea and disturbance of reproductive function." (PMID 29109960, 2017). "Additionally, subgroup analysis based on adenomyosis types revealed significantly higher clinical pregnancy rates, ongoing pregnancy rates and live birth rates in the group receiving oxytocin receptor antagonists compared to the control group among women diagnosed with diffuse adenomyosis." (PMID 38997744, 2024).
adenomyosis (continued). "This research aims to investigate whether administering an oxytocin receptor antagonist during a frozen embryo transfer (FET) cycle using a hormone replacement therapy (HRT) protocol can enhance in vitro fertilization (IVF) outcomes for infertile women affected by adenomyosis." (PMID 38997744, 2024). "The transcriptomic result highlighted the increased OXTR in myometrium and dysregulated ECM changes, collagen degradation and inflammation in the endometrium of women with adenomyosis." (PMID 35773139, 2022). "Multivariate analysis revealed a negative correlation between the use of oxytocin receptor antagonists and early miscarriage rates in women with adenomyosis." (PMID 38997744, 2024).
mental disorder (12 papers, 2016 to 2025). A disease that has its basis in the disruption of mental process. "Several potential genetic markers of susceptibility, such as G allele carriers of OXTR rs53576, are likely to modify air pollution-related mental disorders." (PMID 39058106, 2024). "Oxytocin has an important endocrine role in pregnancy and parturition and methylation of the oxytocin receptor (OXTR) has been linked to mental disorders." (PMID 31805950, 2019). "For instance, recent genetic studies have provided evidence of gene-environment (G × E) interactions, such that the SNPs within the oxytocin receptor gene (OXTR) interact with the environment to confer risk for mental disorders and other behavioral traits." (PMID 27872764, 2016). "Although the A allele of rs53576 of the OXTR gene is likely related to a higher risk of developing mental disorders, the G allele carriers may be more susceptible to air pollution-related mental disorders." (PMID 39058106, 2024). "Epigenetic regulation of the oxytocin and oxytocin receptor (OXTR) gene is altered in several mental disorders and influences social behaviour, often depending on the underlying sex." (PMID 40658054, 2025). "Below, we summarize and discuss the results of studies on the potential roles of OXTR in various mental disorders." (PMID 36835321, 2023). "A comprehensive analysis revealed an enrichment in a network of the expression of genes functionally coupled with OXTR in several mental disorders." (PMID 36835321, 2023). "Brain-derived neurotrophic factor (BDNF), serotonin transporter (SLC6A4), and oxytocin receptor alteration (OXTR) affect major brain systems with a possible expression of related mental disorders." (PMID 35409300, 2022). "Again, it appears, therefore, that the mechanisms of the involvement of dysfunctions of OXTR in major mental disorders might be common, or at least similar." (PMID 36835321, 2023). "Once more, these results corroborate the proposal that changes in OXTR are not specific to any individual mental disorder but rather that they can modulate the course of different diseases by influencing social behaviors and/or cognitive functions." (PMID 36835321, 2023).
Cognitive impairment (8 papers, 2009 to 2024). Abnormal cognition is characterized by deficits in thinking, reasoning, or remembering. "As a result, the effects of OXT and OXTR variants can be observed in humans from prenatal development to adulthood, as well as in daily social interactions seen in individuals with social cognition impairment such as ASD." (PMID 38191308, 2024). "In humans, this A218T mutation of the OXTR has been associated with cognition deficits, differences in emotional empathy, and preterm birth." (PMID 34980886, 2022). "OXTR encode for the oxytocin receptor which in known to be linked to social cognition deficit in SCZ." (PMID 33672396, 2021). "These include positive associations between OXTR DNAm and callous-unemotional traits in youth, social cognitive deficits in ASD, rigid thinking in anorexia nervosa, affect regulation problems and mood deficits as well as limbic regions linked with facial and emotional recognition." (PMID 29843655, 2018). "Furthermore, direct microinjection of oxytocin into the mPFC reversed the social avoidance and cognitive impairment, whereas pre-infusion of the oxytocin receptor antagonist atosiban blocked the reversal effects of oxytocin." (PMID 34566567, 2021).
obsessive-compulsive disorder (8 papers, 2009 to 2024). A disorder characterized by the presence of persistent and recurrent irrational thoughts (obsessions), resulting in marked anxiety and repetitive excessive behaviors (compulsions) as a way to try to decrease that anxiety. "Epigenetic alterations in the OXTR gene are a promising candidate marker for mediating genetic susceptibility to obsessive-compulsive disorder (OCD), which is characterized by recurrent and disturbing obsessions and repetitive compulsive behaviors." (PMID 32631409, 2020). "The aim of this study was to evaluate the association between oxytocin receptor gene single nucleotide polymorphisms or haplotypes and alexithymia in patients with obsessive-compulsive disorder." (PMID 26599592, 2015). "Obsessive-compulsive disorder (OCD) patients showed higher DNA methylation at the CpG site of cg04523291 of OXTR compared to controls." (PMID 37153633, 2023). "Epigenetic alterations in the oxytocin receptor gene (OXTR) may be a molecular mechanism in the pathogenesis of obsessive-compulsive disorder (OCD)." (PMID 32631409, 2020). "In humans, individuals with neurodevelopmental disorders including obsessive-compulsive disorders (OCDs) and ASD exhibited abnormal DNA methylation modification in the OXTR gene." (PMID 37153633, 2023). "Worth mentioning is that, in non-PWS individuals with obsessive compulsive disorder (OCD), changes in the oxytocin receptor have been found, and a methylation of the oxytocin receptor has even been suggested as a biomarker for the response to the treatment of OCD." (PMID 39194735, 2024).
postpartum depression (8 papers, 2015 to 2025). A type of clinical depression that occurs after childbirth. "As far as we know, no studies have assessed the association between the OXTR rs2740210, OXT rs4813627, or OXTR rs237885 polymorphisms and the development of postpartum depression." (PMID 40076753, 2025). "In contrast, increased levels of oxytocin receptor DNA methylation have been shown to occur during pregnancy, and these levels have been associated with an increased risk of postpartum depression in women." (PMID 33327490, 2020). "In summary, the present study indicates an interaction effect of oxytocin receptor genotype (the A allele of OXTR rs53576) × environmental factors in early life (maternal postpartum depression) on child behavioural (externalising) problems." (PMID 31118457, 2019). "Longitudinal studies with replication of this research with other clinical population samples from all over the world, would provide a clearer image of the association between postpartum depression and single nucleotide polymorphisms in the oxytocin/oxytocin receptor gene." (PMID 40076753, 2025). "Furthermore, we applied parallel-processing evaluation for three of the genetic single nucleotide polymorphisms of the oxytocin gene or the oxytocin receptor gene for the occurrence of postpartum depression." (PMID 40076753, 2025). "Our findings add to the evidence that the A allele of OXTR rs53576 genotype is one of the vulnerability biomarkers for predisposition to mental problems in children, in cooperation with environmental burdens such as maternal postpartum depression." (PMID 31118457, 2019). "Furthermore, a few studies have reported that the level of DNA methylation in OXTR is associated with social anxiety, postpartum depression, and facial recognition ability." (PMID 30202991, 2018). "This indicates that an interaction of vulnerable genotypes (i.e., A allele of OXTR rs53576) with an environmental burden (i.e. maternal postpartum depression) may be one of the potential elements that predisposes the infant to developing behavioural problems early in life." (PMID 31118457, 2019). "Therefore, the present finding provides additional evidence supporting the role of the A allele of OXTR rs53576 as a vulnerability marker for developing behavioural problems by operating together with environmental burdens, i.e., maternal postpartum depression." (PMID 31118457, 2019). "Such an interaction of OXTR × maternal postpartum depression remained significant when several covariates were adjusted for: β = −0.185, 95% CI −0.330 to −0.040 for the adjusted final model." (PMID 31118457, 2019). "In the crude model, there was a significant interaction effect of OXTR × maternal postpartum depression on externalising problems (β = −0.210, 95% CI −0.359 to −0.062)." (PMID 31118457, 2019). "We found a significant interaction effect of OXTR genotype and maternal postpartum depression on externalising problems in children." (PMID 31118457, 2019). "Thus, using a unique longitudinal birth cohort sample in Japan (n = 568), we examined whether there was an effect of the interaction between the OXTR rs53576 genotype and maternal postpartum depression, as an environmental risk, on behavioural problems in children." (PMID 31118457, 2019). "Thus, it is plausible that maternal postpartum depression may hamper positive communication between the mother and child during infancy, and the resultant impaired relationship could predispose the child to externalising problems wherein the A allele of OXTR rs53576 genotype may intervene." (PMID 31118457, 2019). "The results obtained showed that polymorphisms in OXT, but not in OXTR, could predict the onset of postpartum depression, and also, could be used as a maternal instrumental care screening tool." (PMID 40076753, 2025). "As hypothesized, the effect of maternal postpartum depression was found for the A allele of OXTR rs53576 genotype, but not for the G allele." (PMID 31118457, 2019).
postpartum depression (continued). "The present study has proposed an investigation into gene–environment interaction effects for the occurrence of postpartum depression and OXT SNP genotypes of rs2740210; rs4813627 and OXTR SNP genotypes of s237885." (PMID 40076753, 2025). "The finding of time-sequential relation, and not cross-sectional relation between maternal postpartum depression and OXTR rs53576 genotype that occurs early in life (i.e. in the neonate) and subsequent behavioural problems in offspring (6 years of age) alludes to the presence of a causal link." (PMID 31118457, 2019). "In addition, these results may differ across populations and cultures, suggesting that the interaction effects between postpartum depression and OXT/OXTR SNP genotypes may also depend on the population; therefore, there may be other different target genes to be considered." (PMID 40076753, 2025).
eating disorder (7 papers, 2017 to 2025). A broad group of psychological disorders with abnormal eating behaviors leading to physiological effects from overeating or insufficient food intake. "For example, Acevedo and colleagues found a correlation between specific single nucleotide polymorphisms (SNPs) of the oxytocin receptor gene (OXTR), and increased severity of eating disorder symptoms in those with AN." (PMID 38685102, 2024). "Eating disorders were found to be linked with oxytocin through leptin in the case of anorexia or through changes in oxytocin receptor genes, as seen in cases of bulimia and anorexia, promoting the idea that oxytocin could be used in treatment." (PMID 35888641, 2022). "Individual OXTR SNP are unlikely in themselves to explain complex eating disorders but may affect the expression of and/or effectiveness of the OXTR." (PMID 34256847, 2021). "Individual OXTR SNPs are unlikely in themselves to explain complex eating disorders but may form part of a haplotype with other OXTR SNPs to affect the expression of and/or effectiveness of the OXTR." (PMID 34256847, 2021). "There is evidence to support that sensitivity to oxytocin, which is thought to be mediated by genetic and epigenetic alterations in the OXTR gene, might play a role in criterion eating disorder behaviours." (PMID 34256847, 2021).
migraine (7 papers, 2020 to 2026). "Apart from the influence of sex hormones, functional interactions between central and peripheral regions related to migraine, estrogen receptors, CGRP receptors, OT and oxytocin receptors (OTR) are suggested." (PMID 36967387, 2023). "The results propose distinct mechanisms affected in migraine, including the TSHR signalling pathway, OXTR signalling pathway, Alzheimer’s disease amyloid secretase pathway, 5HT2R signalling pathway and G-protein signalling pathway combined with activity of interneurons, pyramidal CA1 and SS neurons." (PMID 32968778, 2020).
prostate carcinoma (7 papers, 2011 to 2025). A carcinoma that arises from epithelial cells of the prostate gland. "Furthermore, several genes including FZD4, OPRK1 and OXTR identified here with a growth inhibitory loss-of-function impact on the prostate cancer cells have been recently associated in independent studies with a role in prostate cancer pathogenesis." (PMID 21443765, 2011). "Coupling of OXTR with Gi proteins enables the recognition of oxytocin to induce migration and metastasis in prostate cancer." (PMID 34877409, 2021). "Accordingly, the activation of oxytocin receptor has been found to elevate the invasive properties of endometrial cancer cells via the PI3K/Akt axis and to promote the migratory ability of prostate cancer cells by coupling to the Gi-dependent pathway." (PMID 28576130, 2017).